CXCL10 (C-X-C motif chemokine ligand 10)
Diseases named in the same sentence as CXCL10 in open-access papers (continued):
Sharing a sentence is not in itself a finding about the gene and the disease.
Granuloma (21 papers, 2005 to 2025). A compact, organized collection of mature mononuclear phagocytes, which may be but is not necessarily accompanied by accessory features such as necrosis. "The upregulation of CXCL10, associated with “regulation of monocyte chemotaxis”, aligns with previous findings on the roles of IFN-γ in granuloma formation." (PMID 41463010, 2025). "Previous experiments have demonstrated that Mtb-infected dendritic cells produce CXCL10, which acts as a chemotactic factor for NK cells and T lymphocytes (both CD4+ and CD8+), that contribute to the formation of TB granulomas at the infection site." (PMID 40668059, 2025). "Previous research indicates that mycobacterial infection induces the release of chemokines like CXCL10 and CXCL11, crucial for immune mediator formation and granuloma development in TB-specific T cells." (PMID 40463504, 2025). "CXCL10 and CCL4 facilitate the migration of Th1 and CD8+ T cells to the granuloma (Soong, Henard and Melby, 2012), while CXCL9 recruits CD8+ T cells, Th1 cells, and NK cells, amplifying the immune response in granuloma areas." (PMID 40556761, 2025). "Previous studies indicated that IFNγ mediates expression and secretion of chemokines CXCL9, CXCL10, and CXCL11 in macrophages, resulting in the recruitment of CXCR3 bearing CD4+ Th cells and CD8+ Tc cells into the lung and granuloma formation in humans and mice." (PMID 39464896, 2024). "Additionally, upregulated in early stages of granuloma development are CXCL9 and CXCL10 (also knowns at interferon gamma-induced protein 10 (IP-10)), both potent chemokines for lymphocytes and macrophages." (PMID 35056009, 2022). "However, the levels of CXCL10 and CCL5, readout cytokines of the MyD88-independent TLR4 pathway increased at week 5 when Sj eggs induce granuloma and then at week 6 when Sj eggs induce acute liver damage." (PMID 29321784, 2017). "Furthermore, recent data in the animal model suggest that CXCR3/CXCL9, CXCL10, CXCL11 interactions are central in the pathogenesis of hypersensitivity reactions to Saccharopolyspora rectivirgula (SR) and successive granuloma formation." (PMID 15725351, 2005). "In mice models of granulomatous disease induced by Propionobacterium acnes, CXCL10 has been shown to be necessary for the formation of Th1 lymphocyte clusters in draining lymph nodes, and blockade of CXCR3 (the receptor for CXCL9 and CXCL10) and CCR5, inhibits the formation of granulomas in lungs." (PMID 24199653, 2013). "The expression levels of CXCL10, CXCL11, CCR7, CCL17 and CCL18 in the tuberculous granuloma were measured by quantitative real-time RT-PCR and were compared with the levels detected in lung tissues without granulomas." (PMID 26091535, 2015).
leprosy (21 papers, 2009 to 2025). Leprosy is a chronic infectious disease affecting primarily the skin and peripheral nervous system. "The purpose of this systematic review is to assess CXCL10’s potential utility as a leprosy diagnostic tool and evaluation of therapy." (PMID 38590701, 2024). "The increase in CXCL10 levels in peripheral blood has been associated with neuritis during leprosy reactions." (PMID 38381878, 2024). "IFN-γ and CXCL10 were evaluated as potential diagnostic host markers for PB leprosy patients in the hyper-endemic regions of Brazil and China." (PMID 30248098, 2018). "Although there are some studies about CXCL10 as diagnostic biomarkers of leprosy and as MDT effectiveness’ parameter, further studies to investigate its’ properties in larger populations (endemic and non-endemic settings) with consideration should be conducted." (PMID 38590701, 2024). "Besides assessing MDT effectiveness’ in leprosy patients, CXCL10 could be used as one of diagnostic biomarker for leprosy." (PMID 38590701, 2024). "Using UCP-LFA, CXCL10 was higher in response to M. leprae antigen and higher CXCL10/IL-10 ratio in leprosy patient compared to endemic control (EC)." (PMID 38590701, 2024). "When activated, CXCL10 modulated the formation and development of different types of granulomas and spectrum disease during the evolution of leprosy." (PMID 38590701, 2024). "Meanwhile, painless leprosy neuropathy had significantly higher concentration of CXCL10 than leprosy patients with neuropathy (p = 0.02)." (PMID 38590701, 2024). "According to this study, in both low- and high-endemic communities, CXCL10 was the most important cellular marker for identifying leprosy patients with LL/BL and BT/TT." (PMID 38590701, 2024). "CXCL10 can recruit effector Th1 cells to the site of delayed type hypersensitivity and previously has been identified in tuberculoid lesions of leprosy patients." (PMID 38590701, 2024). "Identifying CXCL10 can be convenient through easily accessible lateral flow assays, rendering it a feasible indicator for detecting leprosy." (PMID 38590701, 2024). "In this study, CXCL10 mRNA levels were consistently high across all leprosy subgroups, but reaching >500 times in BB-T1R." (PMID 38590701, 2024). "Twenty articles were included in the qualitative synthesis process of this systematic review, which evaluated the potential contribution of CXCL10 in diagnosing leprosy and leprosy therapy." (PMID 38590701, 2024). "Involvement of a chemokine known as C-X-C motif chemokine ligand 10 or CXCL10 in the immunopathology of leprosy has emerged as a possible immunological marker for leprosy diagnosis and needed to be investigate further." (PMID 38590701, 2024). "CXCL10 is typically elevated in response to Mycobacterium leprae infection, so it has potential to be a biomarker for leprosy." (PMID 38590701, 2024). "The scope of this study investigation into CXCL10’s function in leprosy diagnosis was restricted to humans." (PMID 38590701, 2024). "Presence of CXCL10 in leprosy patients can help establish a diagnosis apart from using clinical diagnosis criteria." (PMID 38590701, 2024). "The results presented in this systematic review supports the importance of CXCL10 in leprosy diagnosis, particularly in leprosy responses and in tracking the efficacy of MDT therapy." (PMID 38590701, 2024). "Studies discovered that CXCL10 was expressed in borderline tuberculoid (BT), mid-borderline (BB), borderline lepromatous (BL), and lepromatous (LL) leprosy skin lesions with varying levels and also increased in paucibacillary (PB) leprosy patients’s plasma." (PMID 38590701, 2024). "The detection of CXCL10 in leprosy patient can also be done using rt-PCR, ELISA, whole blood assay, and histopathological evaluation using immunostaining." (PMID 38590701, 2024). "Yet the findings are heterogenous, thus more investigation is required to determine the roles of CXCL10 in leprosy while taking into account for additional confounding variables." (PMID 38590701, 2024).
leprosy (continued). "In conclusion, the included studies in this systematic review has demonstrated CXCL10’s role in diagnosing leprosy, particularly in leprosy reactions." (PMID 38590701, 2024). "Future research focusing on the development of these tools and CXCL10 as a biomarker in diagnosing different types of leprosy is needed due to the varying outcomes of the included studies, making it difficult to draw certain conclusions." (PMID 38590701, 2024). "A gene set signature involving bacterial genes ML2388, ML2664, and host immune genes CXCL10 and IL-17A can be transcriptomic markers for reactional states in leprosy." (PMID 37051521, 2023). "In conclusion, we recommend bacterial genes ML2388, ML2664, and host immune genes CXCL10 and IL-17A as transcriptomic signatures for reactional states in leprosy." (PMID 37051521, 2023). "Identifying a host biomarker signature to support diagnosis has made a significant advance, with high titters of anti-PGL-1 IgM, IP-10/CXCL-10 and CRP being associated with leprosy." (PMID 35416839, 2022). "These markers of innate immunity (CXCL10) and infection (FCGR1A) thus are increased in two different phases in leprosy associated either with M. leprae-specific T cell anergy and high bacterial load (BL/LL) or with a highly inflammatory state (RR)." (PMID 31784594, 2019). "Therefore, this systematic review was conducted in order to draw conclusions from all studies about the relevance of CXCL10 in the diagnosis of leprosy, determining the types of leprosy, and as indicator of the efficacy of leprosy therapy." (PMID 38590701, 2024). "There are several studies focusing on using CXCL10 as one of biomarkers use in diagnosing leprosy." (PMID 38590701, 2024). "Similar outcomes were obtained using fingerstick blood for UCP-LFA, and CXCL10 continued to be an important marker in plasma for MB patients, which means we could use fingerstick blood as a sample in diagnosis of leprosy." (PMID 38590701, 2024). "With varying levels of CXCL10, it’s potentially useful to help differentiate types of leprosy." (PMID 38590701, 2024). "Most of studies indicate that CXCL10 may be a helpful immunological marker for leprosy diagnosis, particularly in leprosy reactions as stated in seven studies." (PMID 38590701, 2024). "Expression of CXCL10 were found to be higher in leprosy patients than control or household contact." (PMID 38590701, 2024). "According to histological results, pure neural leprosy (PNL) nerves showed CXCL10 expression." (PMID 38590701, 2024). "According to research, CXCL10 is an immune marker also linked to neural leprosy despite not being explicitly linked to fibrosis in neural leprosy." (PMID 38590701, 2024). "Included studies used in this systematic review were investigating CXCL10 levels in different types of leprosy, between leprosy patients and control, between leprosy with reaction and without reaction, before and after MDT treatment, and in field friendly diagnostic tools." (PMID 38590701, 2024). "Several studies revealed the upregulation of CXCL10 (IP10) in reactional states of leprosy." (PMID 37051521, 2023). "In fact, CXCL10 has been pointed out as a significant biomarker to identify leprosy patients." (PMID 37187734, 2023). "This is the first observation of high levels of circulating CXCL10 in leprosy." (PMID 19473542, 2009). "Using CXCL10 in clinical settings might help with leprosy early diagnosis." (PMID 38590701, 2024). "Additionally, CXCL10 may be utilized to assess the efficacy of multidrug therapy (MDT) in leprosy patients as stated in three studies." (PMID 38590701, 2024). "In PB leprosy patients and healthy household contacts who are frequently exposed to M. leprae, IFN-γ production is stimulated which results in release of CXCL10." (PMID 38590701, 2024). "The elevated level of circulating cytokines CXCL10 and IL6 act as promising markers for leprosy in T1R." (PMID 33573064, 2021).
leprosy (continued). "This survey of circulating cytokines has identified elevations in CXCL10 and IL6 as promising markers for leprosy T1R." (PMID 19473542, 2009). "Elevated levels of the chemokine CXCL10 were observed in PB and MB patients in relation to the group of individuals without a clinical history of leprosy." (PMID 40109344, 2025). "This study found significantly higher levels of CXCL10 (p < 0.05) in skin lesion of leprosy patients with Type 1 reaction (T1R) compared to no reaction cases (NR)." (PMID 38590701, 2024). "Additionally, we observed that a classification of leprosy patients is possible using transcriptomics since a set of genes were increased in BL/LL patients (CD46, CXCL10, FCGR1A, HDAC2 and TLR4) and TT/BT showed a higher expression of IL2 and TLR6." (PMID 31784594, 2019). "In the case of leprosy, we believe that the mediators CXCL8, CCL3, CXCL10, IL-9, IL-6, and IFN-γ could be considered as potential biomarkers for the future development of rapid assays that could assist in the diagnosis and prognosis of leprosy and leprosy reactions." (PMID 40109344, 2025). "Compared to non-reactional BB leprosy, T1R biopsies showed more pronounced CXCL10 staining." (PMID 38590701, 2024). "There was no CXCL10 and CCL2 expression found in the nerve sections of non-leprosy group." (PMID 38590701, 2024).
endometriosis (20 papers, 2013 to 2025). The growth of functional endometrial tissue in anatomic sites outside the uterine body. "As neoangiogenesis is a requirement for intraperitoneal endometriosis lesions to survive, numerous angiogenic involving VEGF and other factors and proinflammatory cytokines, including IL-8 and CXCL10, are overexpressed in ectopic endometriosis lesions." (PMID 36762287, 2023). "Endometriosis was also associated with elevated concentrations of IL-6, IL-10, and TGF-β1/2 as well as CCL20, CXCL8, CXCL9, and CXCL10." (PMID 34501240, 2021). "Both in serum and in PF, CXCL10 has been found to be significantly decreased in advanced stages of endometriosis compared to controls." (PMID 32604857, 2020). "It is possible that the increased levels of MMP-9 in endometriosis result in cleavage and degradation of CXCL9 and CXCL10, causing decreased levels of these proteins." (PMID 30621017, 2019). "Previous studies have reported significantly lower concentrations of the closely related CXCL9 and CXCL10 (also called IP-10) in peripheral blood in endometriosis, in line with the present study." (PMID 30621017, 2019). "The inflammatory peritoneal environment contributes to the colonization of endometriosis lesions, and the peritoneal fluid contains high levels of cytokines and growth factors, such as interferon-gamma-induced protein-10 (CXCL10), IL-8, and chemokine growth-regulated-alpha (GRO-α)." (PMID 36762287, 2023). "In addition, IL-17, CXCL10 (IP-10) and IL-23 are known to induce inflammation in endometriosis by enhancing the migration of granulocytes." (PMID 37762161, 2023). "The levels of angiogenin, CD105, ICAM-1, CXCL10, leptin, lipocalin-2, MMP-9, osteopontin, RBP4, PAI-1, ABP, CD31, TIM-2, and VCAM-1 were higher in the endometriosis group than in the control group." (PMID 34072419, 2021). "We also reported that the peritoneal fluid of patients with endometriosis showed significantly increased concentrations of CCL20, CXCL9, and CXCL10." (PMID 34501240, 2021). "The evaluation of chemokines showed that the peritoneal fluid from patients with endometriosis displayed significantly higher concentrations of CCL20, CXCL8, CXCL9, and CXCL10." (PMID 34501240, 2021). "There is increased expression of MMP-9 in endometrium and in peritoneal fluid in endometriosis, and MMP-9 cleaves CXCL9 at three different sites and degrades CXCL10." (PMID 30621017, 2019). "Once neutrophils reach the peritoneal fluid and ectopic endometriosis lesions, they participate in the inflammatory process of endometriosis by secreting pro-inflammatory cytokines like IL-8, VEGF, and C-X-C motif chemokine ligand 10 (CXCL-10), all of which enhance the progression of the disease." (PMID 40747182, 2025). "In endometriosis, PEA technology identified seven proteins up-regulated (IL-6, IL-8, CCL 19, SCF, VEGF-D, IL-6RA, MIA9) and ten proteins down-regulated (ICOSLG, EGFR, SELE, ErbB2/HER2, IL-6RA, VEGFR-2, Flt3L, CXCL10, HE4, FR-alpha)." (PMID 36009404, 2022). "Specifically, pro-inflammatory cytokines, chemokines and receptors including CXCL1, CX3CL1, CXCL9, CXCL10, IL-32, CXCR2, IL-7R and adhesion molecules including ICAM3 and SELL had a higher expression in the eutopic endometrium of infertile, endometriosis patients compared to fertile controls." (PMID 27740937, 2017). "Neutrophils aggravate endometriosis mainly through the expression of pro-inflammatory cytokines such as interleukin 8 (IL-8 or CXCL8), C-X-C motif chemokine ligand 10 (CXCL10) and vascular endothelial growth factor (VEGF), which may promote disease progression." (PMID 37446108, 2023).
lupus nephritis (20 papers, 2010 to 2025). Glomerulonephritis in the context of systemic lupus erythematosus. "In addition, the diagnostic value of CXCL10 or CXCR3 in lupus nephritis was proposed in animal experiments." (PMID 32089645, 2020). "Moreover, overexpression of CXCL10 is associated with clinical lupus nephritis." (PMID 37790939, 2023). "CXCL10 was considered a highly valid predictor of SLE nephritis with high sensitivity (100%) and specificity (98%)." (PMID 32089645, 2020). "CCL2 (also known as monocyte chemotactic protein-1, MCP-1) and CXCL10 are good biomarkers to indicate the activity of lupus nephritis and the potential flares in SLE." (PMID 26310926, 2015). "Furthermore, C3-LHF1 potentiated tumor necrosis factor (TNF)-induced C-X-C motif chemokine ligand 10 (CXCL10) secretion and decreased markers of healthy podocytes, suggesting a role in podocyte injury and inflammatory tissue remodeling characteristic of lupus nephritis." (PMID 41249507, 2025). "In addition, CXCL10 has been shown to be a significant biomarker of disease severity, and it can be used as a prognostic indicator for a variety of renal diseases, such as renal allograft dysfunction and lupus nephritis." (PMID 32089645, 2020). "Furthermore, CXCL10 has been identified as a major biological indicator of disease severity and may be utilized as a prognostic indicator for diseases such as renal allograft dysfunction and lupus nephritis (LN)." (PMID 32089645, 2020). "The expression level of chemokines like CXCL11—Interferon-inducible T cell α-chemoattractant (I-TAC), CXCL13—B-lymphocyte chemoattractant (BLC), CXCL10 (IP-10) and CCL3 (MIPα), correlate with disease activity (especially lupus nephritis (LN))." (PMID 26473848, 2015). "We found EZH2 was upregulated in renal biopsies from lupus nephritis patients as compared with normal para-carcinoma kidney tissues; and there were significant positive correlations between the expression of EZH2 and CXCL10 or IFIT3, respectively." (PMID 33868295, 2021).
type 2 diabetes (20 papers, 2008 to 2025). "Elevated levels of CXCL10 have been found in the serum of patients with newly diagnosed type 1 or type 2 diabetes and in patients at high risk of developing the disease." (PMID 40597598, 2025). "Similarly, CXCL10, IL-22, IL-21, and IL-1α were negatively associated with the need for mechanical ventilation and coma duration." (PMID 41219650, 2025). "Genes in the CXCL10 low-expression group were mainly enriched in metabolic pathways, such as nitrogen metabolism, maturity onset diabetes, and glycosylphosphatidylinositol." (PMID 36782176, 2023). "Selective DPP4 inhibitors are marketed for the treatment of type 2 diabetes, and—as shown by us and others—this class of drugs can abrogate the truncation of CXCL10 by DPP4 in vitro and in vivo." (PMID 30026741, 2018). "This appears to be a class effect as rosiglitazone, which is currently used to treat people with type II diabetes mellitus, also inhibited cytomix-induced CXCL10 release." (PMID 23034049, 2012). "Patients with type 2 diabetes mellitus (T2DM) have been found to have higher levels of CXCL10 in meta-analysis research." (PMID 37928902, 2023). "Moreover, CXCL10 was reported to induce beta-cell apoptosis in type 2 diabetes." (PMID 36059840, 2022). "After merging and filtering across datasets, 13 genes were found to be consistently upregulated in both ulcerative colitis and type 2 diabetes, with CXCL9, S100A8, CXCL10, CHI3L1, and SLC6A14 showing the most significant alterations." (PMID 41155631, 2025).